METTL13 (methyltransferase 13, eEF1A N-terminus and K55)
Description:
Dual methyltransferase that catalyzes methylation of elongation factor 1-alpha (EEF1A1 and EEF1A2) at two different positions, and is therefore involved in the regulation of mRNA translation. Via its C-terminus, methylates EEF1A1 and EEF1A2 at the N-terminal residue 'Gly-2'. Via its N-terminus dimethylates EEF1A1 and EEF1A2 at residue 'Lys-55'. Has no activity towards core histones H2A, H2B, H3 and H4.
Synonyms: EEF1AKNMT; FEAT; KIAA0859; CGI-01; 5630401D24Rik; DFNB26; DFNB26M; DFNM1
Tractability: Small molecule: a structure with a bound ligand is known. PROTAC: ubiquitination databases record sites on it; its protein half-life has been measured.
Gene: Protein-coding gene on chromosome 1 (171,781,660 to 171,814,023, forward strand). Ensembl gene ENSG00000010165.
Subcellular location: Cytoplasm; Nucleus; Mitochondrion
Subcellular location (Human Protein Atlas): Cytosol
Gene Ontology:
Molecular function: protein binding; protein-lysine N-methyltransferase activity
Cellular component: cytoplasm; cytosol; mitochondrion; nucleus
Genetic constraint (gnomAD): Loss-of-function variants: 52 observed, 69.06 expected, observed/expected ratio (o/e) 0.75, 90% interval 0.6 to 0.95. The upper end of that interval is the gene's LOEUF score, 0.95, which puts it in group 4 of 6, group 1 being the genes least tolerant of losing a copy. Missense variants: 825 observed, 919.44 expected, observed/expected ratio (o/e) 0.9, 90% interval 0.85 to 0.95. Synonymous variants: 354 observed, 365.11 expected, observed/expected ratio (o/e) 0.97, 90% interval 0.89 to 1.06.
Homologues: Orthologues: chimpanzee METTL13 (99% identical), macaque METTL13 (98% identical), rabbit METTL13 (94% identical), pig METTL13 (94% identical), dog METTL13 (94% identical), guinea pig METTL13 (92% identical), mouse Mettl13 (90% identical), rat Mettl13 (90% identical), tropical clawed frog mettl13 (57% identical), zebrafish mettl13 (53% identical), Drosophila melanogaster CG2614 (42% identical), Caenorhabditis elegans metl-13 (33% identical). Paralogues in human: EEF1AKMT4 (12% identical), CSKMT (8% identical).
Diseases named in the same sentence as METTL13 in open-access papers:
METTL13 is named in the same sentence as 46 diseases in open-access papers, as found by Europe PMC text mining. Sharing a sentence is not in itself a finding about the gene and the disease. The quoted sentences say what the papers report.
hepatocellular carcinoma (9 papers, 2015 to 2024). A malignant tumor that arises from hepatocytes. "METTL13, which is also annotated as FEAT has anti-apoptotic functions and has been linked to cirrhotic lesions in the human liver adjacent to hepatocellular carcinoma (HCC) tissue, suggesting a role in inflammation." (PMID 32039196, 2019). "In hepatocellular carcinoma, a positive feedback loop involving METTL13, eEF1A, and HN1L has been identified." (PMID 39155349, 2024). "In 2019, scholars demonstrated that expression of METTL13 is positively regulated at transcriptional level by HN1L and METTL13 can enhance hepatocellular carcinoma development by up-regulating TCF3 and ZEB1." (PMID 33985542, 2021). "The unusual m6A modification caused by differentially expressed METTL13 or METTL14 plays a critical role in the malignant progression of various cancers, such as bladder cancer, gastric cancer, and hepatocellular carcinoma (HCC)." (PMID 33159022, 2020). "More interestingly, a recent report has shown that METTL13 also serves as a crucial mediator of HN1L in modulating hepatocellular carcinoma cell growth and metastasis via interacting with AP-2γ, raising a possibility that METTL13 and HN1L forms a positive feedback regulatory loop." (PMID 35925508, 2023). "In addition, we also found HN1L could facilitate METTL13 expression in GC cells consistent with a previous report in hepatocellular carcinoma." (PMID 35925508, 2023). "Inconsistencies between the levels of METTL13 protein and its mRNA have been observed in lung cancer, breast cancer, and liver cell carcinoma, showing a negative correlation." (PMID 39155349, 2024). "More recently, METTL13 has been shown as a crucial mediator of HN1L (hematological and neurological expressed 1-like) in modulating hepatocellular carcinoma (HCC) cell growth and metastasis via co-activating TCF3 (transcription factor 3) and ZEB1 (zinc finger E-box binding homeobox 1) expression." (PMID 35925508, 2023).
breast cancer (7 papers, 2015 to 2025). A primary or metastatic malignant neoplasm involving the breast. "In fact, the upregulation of METTL13 has been detected in many cancers and is associated with worse prognoses, such as breast cancer, head and neck squamous cell carcinoma, nasopharyngeal carcinoma, and gastric cancer." (PMID 40382345, 2025). "In liver, pancreatic, gastric, and breast cancer, METTL13 is highly expressed and is associated with poor patient survival." (PMID 39711977, 2024). "However, METTL13 expression did not significantly differ between HER2-negative and HER2-positive breast cancers, and SETDB1 is a well-known potential modulator of breast cancer metastasis." (PMID 39309445, 2024).
lung carcinoma (7 papers, 2015 to 2025). "Especially, METTL13 can mediate the methylation of eEF1A at the N terminus and lysine 55 (eEF1AK55me2), and eEF1AK55me2 is increased in pancreatic and lung cancers and associated with poor clinical outcomes." (PMID 40382345, 2025). "In 2016, researchers detected high expression levels of METTL13 in the plasma of patients with breast, ovarian and lung cancer, following which it was identified as a recurrence predictor for breast cancer." (PMID 33985542, 2021). "Purified from rat livers in 2011 by a Japanese researcher, METTL13 was found to be abnormally overexpressed in several human cancers including lung cancer and to drive tumorigenesis in transgenic mice." (PMID 33985542, 2021). "In DMG cells, we found that upregulation of the methyltransferase METTL13 leads to high levels of methylation of the translation regulator EEF1A1 which, consistent with previous reports in Ras-driven pancreatic and lung cancer models, was accompanied by increased rates of protein synthesis." (PMID 39954016, 2025).
pancreatic cancer (6 papers, 2021 to 2025). "METTL13 was found to be upregulated in liver, breast, lung and pancreatic cancer, which was significantly associated with patient poor survival." (PMID 35925508, 2023). "METTL13 has been correlated with a decreased survival probability in malignancies such as lung and pancreatic cancer and to augment metastasis in gastric cancer." (PMID 41282185, 2025). "For example, increased eEF1A K55 methylation by overexpression of METTL13 plays a central role in the development of lung and pancreatic cancers." (PMID 38199565, 2024). "In humans, increased levels of METTL13 and eEF1AK55me2 correlate with poor survival of patients with lung or pancreatic cancer." (PMID 37347777, 2023). "The Ras-mediated cancers utilize the METTL13-eEF1AK55me2 dimethylation axis to increase the translational output, and enhance protein synthesis to promote pancreatic cancer progression." (PMID 37396042, 2023). "Another research in lung and pancreatic cancer patient-derived xenograft models further indicated that METTL13 depletion markedly inhibited KRAS-driven pancreatic tumorigenesis." (PMID 35925508, 2023).
gastric cancer (5 papers, 2023 to 2025). A primary or metastatic malignant neoplasm involving the stomach. "METTL13 may become a promising diagnostic and therapeutic biomarker for gastric cancer in the future." (PMID 35925508, 2023). "Wu et al15 showed that METTL13 promoted the growth and metastasis of gastric cancer cells through the eEF1A/HN1L-positive feedback loop." (PMID 39128086, 2024). "METTL13 knockdown inhibited gastric cancer cell proliferation and metastasis both in vivo and in vitro." (PMID 39711977, 2024). "These collective findings indicated that METTL13 plays potential important role in gastric cancer development." (PMID 35925508, 2023). "To evaluate the role of METTL13 in gastric cancer, we detected the protein expression of METTL13 in five kinds of GC cell lines by western blotting." (PMID 35925508, 2023). "METTL13 was upregulated in most gastric cancer tissues compared to the corresponding adjacent normal stomach tissues by qRT-PCR and immunohistochemistry analysis." (PMID 35925508, 2023). "Biological experiments showed that silencing METTL13 suppressed gastric cancer cell proliferation and metastasis in vivo and vitro, whereas opposite effects were observed upon METTL13 overexpression." (PMID 35925508, 2023). "Given that the increased expression of METTL13 in cancer tissues, the role of METTL13 in gastric cancer were subsequently investigated." (PMID 35925508, 2023). "The results of in vitro experiments showed that gastric cancer cells proliferation and migration ability were promoted following METTL13 overexpression." (PMID 35925508, 2023). "Knockdown of HN1L dampened gastric cancer cell growth induced by METTL13." (PMID 35925508, 2023). "To investigate METTL13 expression in GC, we collected 48 pairs of human gastric cancer samples and paired normal adjacent gastric tissues from diagnosed patients and examined the expression of METTL13 via qRT-PCR." (PMID 35925508, 2023).
clear cell renal cell carcinoma (4 papers, 2021 to 2025). "In contrast, loss of METTL13 was considered a poor prognostic marker in clear cell renal cell carcinoma, inhibiting proliferation and metastatic capacity of cancer cells." (PMID 41282185, 2025). "Overexpression of METTL13 decreased the proliferation, migration, and invasion of clear cell renal cell carcinoma cells and inhibited the development of epithelial–mesenchymal transition." (PMID 39711977, 2024). "Based on these, we identify METTL13 as a tumor suppressor gene in clear cell renal cell carcinoma, affecting a variety of biological behaviors of cancer cells and contrary to its role in most other cancers." (PMID 33985542, 2021). "Collectively, our research demonstrated METTL13’s tumor suppressing role in clear cell renal cell carcinoma for the first time, as featured by inhibiting growth and metastasis of cancer cells." (PMID 33985542, 2021).
liver cancer (4 papers, 2021 to 2024). An epithelial or non-epithelial malignant neoplasm that arises from the liver. "A study indicated that METTL13 inhibits apoptosis of lung, breast and liver cancer cells and miR-16 can repress the expression of METTL13 by binding to its 3′-untranslated region." (PMID 33985542, 2021). "In liver cancer, the METTL13-eEF1A-HN1L complex forms a positive feedback loop." (PMID 39155349, 2024). "Notably, miR-16 binding to the 3' end of METTL13 inhibits its expression, hence regulating the EMT and NF-κB signaling pathways to suppress liver cancer cell growth." (PMID 39155349, 2024). "The Cox risk score and clinical characteristic analysis confirmed that ZC3H13, METTL13, and YTHDF2 could be used as prognostic indicators and even as targets for new treatment of liver cancer." (PMID 34055974, 2021).
bladder cancer (3 papers, 2016 to 2024). "Zhang et al16 showed that METTL13 was downregulated in bladder cancer and inhibited cell proliferation, migration, and invasion." (PMID 39128086, 2024). "Although a recent report has demonstrated downregulation of FEAT (METTL13) in bladder carcinoma, specimens obtained from >3 cm from the tumors were used as normal controls." (PMID 27659353, 2016).
deafness (3 papers, 2010 to 2021). An inherited or acquired condition characterized by the complete loss of the ability to hear from one or both ears. "For example, a dominant variant of METTL13 (DFNM1) completely suppresses recessive non-syndromic deafness DFNB26, associated with a variant of GAB2 with both genes functioning in the HGF/MET signaling pathway." (PMID 32987832, 2020). "By analogy with DNFM1/METTL13, which acts as a dominant suppressor of recessive DFNB26/GAB1 deafness, it is intriguing to speculate about the existence of a dominant modifier of SLC22A4, which could suppress the onset of deafness in the non-penetrant individual from family NSHL7." (PMID 33643381, 2021).
leukemia (3 papers, 2025 to 2026). A malignant (clonal) hematologic disorder, involving hematopoietic stem cells and characterized by the presence of primitive or atypical myeloid or lymphoid cells in the bone marrow and the blood. "Excitingly, METTL13 deficiency resulted in poor proliferation capability of the leukemia cell lines as assessed by representative growth images and cell number counting." (PMID 40382345, 2025). "As the role and prognostic effect of METTL13 in pediatric leukemia is unexplored, we dived into the mechanistic link between METTL13 and leukemia propagation using T-ALL as a model." (PMID 41282185, 2025). "METTL13 knockdown significantly reduced the leukemia engraftment rate in bone marrow (29.9% in control and 14.4% in shMETTL13) and spleen (15.6% in control and 2.4% in shMETTL13) (mean values)." (PMID 41282185, 2025). "Thus, we confirmed that METTL13 is important for leukemia proliferation in both in vitro and in vivo T-ALL models." (PMID 41282185, 2025). "The results from the pathway analysis, together with both the in vitro and in vivo validation, highlight the potential impact METTL13 could have on leukemia cell survival and proliferation." (PMID 41282185, 2025). "Knockdown of METTL13 significantly reduced the leukemia engraftment rate in the CDX model." (PMID 41282185, 2025). "However, research on METTL13 and its role in HSC biology and leukemia is sparse." (PMID 41282185, 2025).
acute lymphoblastic leukemia (2 papers, 2025 to 2026). Leukemia with an acute onset, characterized by the presence of lymphoblasts in the bone marrow and the peripheral blood. "Next, we investigated the role of METTL13 in pediatric acute lymphoblastic leukemia (ALL) and found that increased METTL13 expression correlated with a poor prognosis in both T-ALL and B-cell ALL (B-ALL)." (PMID 41282185, 2025). "Furthermore, METTL13 expression was associated with a high-risk profile in pediatric T-cell acute lymphoblastic leukemia (T-ALL) and functional studies confirmed that METTL13 is required for T-ALL cell proliferation and survival both in vitro and in vivo." (PMID 42031695, 2026). "Furthermore, METTL13 was associated with a high-risk profile in pediatric T-cell acute lymphoblastic leukemia (T-ALL), and functional studies confirmed that METTL13 is required for T-ALL cell proliferation and survival both in vitro and in vivo." (PMID 41282185, 2025).
acute myeloid leukemia (2 papers, 2021 to 2025). Acute myeloid leukemia (AML) is a group of neoplasms arising from precursor cells committed to the myeloid cell-line differentiation. "METTL13 deletion and eEF1AK55me2 loss dramatically reduce Ras-driven neoplastic growth in mouse models and in patient-derived xenografts from primary pancreatic and lung tumors, in line with findings in AML-193 and Kasumi-1 cells supporting the implication of eEF1A2K55me2 in acute myeloid leukemia." (PMID 34203525, 2021).
pancreatic duct adenocarcinoma (2 papers, 2023 to 2025). "Furthermore, the loss of METTL13 function in xenograft mouse models, and depletion of pancreatic METTL13 in a mouse model of Ras-driven pancreatic duct adenocarcinoma (PDAC), were shown to suppress tumor growth." (PMID 37347777, 2023). "Moreover, METTL13/METTL14/WTAP complexes and YTHDF2 facilitate PIK3CB mRNA and protein expression levels, significantly promoting the proliferation and migration of PTEN-deficient pancreatic ductal adenocarcinoma cells." (PMID 39806412, 2025).
acute leukemia (1 paper, 2025). A clonal (malignant) hematopoietic disorder with an acute onset, affecting the bone marrow and the peripheral blood. "METTL13 knockdown also altered genes belonging to disease ontologies involved in hematological malignancies, mainly lymphoid leukemias and acute leukemias." (PMID 41282185, 2025).
colon cancer (1 paper, 2025). "METTL13 knockdown also downregulated CEACAM6, which regulates tumor proliferation and migration through ERK-MAPK and PI3K-AKT signaling in several cancers, including lung and colon cancer." (PMID 41282185, 2025).
encephalitis (1 paper, 2025). An acute inflammatory process affecting the brain parenchyma. "ORA of METTL13 knockdown also revealed involvement of METTL13 in several disease ontologies, many related to infection and inflammation, like encephalitis and pneumonia (Fig. SF4B)." (PMID 41282185, 2025).
gastric tumor (1 paper, 2023). "To test this hypothesis, we analyzed METTL13 or HN1L mRNA expression using transcripts per million (TPM) data based on TCGA database which consists of 408 gastric tumor and 211 normal gastric tissue by GEPIA online tool." (PMID 35925508, 2023).
glioblastoma (1 paper, 2016). The most malignant astrocytic tumor (WHO grade IV). "miR-16 has an important role in regulating apoptosis in different cancer types including lung, breast, liver, glioblastoma, and squamous cell carcinoma through targeting FEAT/METTL13, RPS6KB1, IGF1R, CCND1, BCL2, RECK, and/or SOX6." (PMID 27128908, 2016).
liposarcoma (1 paper, 2025). A usually painless malignant tumor that arises from adipose tissue. "Indeed, CRISPR knockout studies have demonstrated that METTL13 was not an essential gene in normal cell lines but more likely to be essential in osteosarcoma, diffuse glioma, non-Hodgkin lymphoma, melanoma, and liposarcoma cell lines (DepMap: Cancer dependency map60,61)." (PMID 39954016, 2025).
lung adenocarcinoma (1 paper, 2025). A carcinoma that arises from the lung and is characterized by the presence of malignant glandular epithelial cells. "METTL1, METTL3, METTL4, METTL5, METTL6 and METTL13 were associated with poor prognosis in various tumors including liver hepatocellular carcinoma (LIHC), breast invasive carcinoma (BRCA), and lung adenocarcinoma (LUAD)." (PMID 41194259, 2025).
metastatic tumors (1 paper, 2021). "The result showed that lungs excised from mice in the METTL13 overexpression group were observed with presence of fewer metastatic tumors, suggesting METTL13’s inhibitory effect on metastatic ability of ccRCC cells." (PMID 33985542, 2021).
myocardial infarction (1 paper, 2025). Gross necrosis of the myocardium, as a result of interruption of the blood supply to the area, as in coronary thrombosis. "In myocardial infarction (MI) models, METTL13 overexpression restores calcium transients and SERCA2a levels, whereas METTL13 knockdown exacerbates cardiac contractile dysfunction." (PMID 39803908, 2025).
non-small cell lung carcinoma (1 paper, 2022). A group of at least three distinct histological types of lung cancer, including non-small cell squamous cell carcinoma, adenocarcinoma, and large cell carcinoma. "The m6A methyltransferase METTL13 positively regulates autophagic flux by upregulating the expression of LC3B, ATG5, and ATG7 and plays a key role in β-elemene reversal of gefitinib resistance in non-small cell lung cancer." (PMID 36263177, 2022).
prostate carcinoma (1 paper, 2025). A carcinoma that arises from epithelial cells of the prostate gland. "KEGG analysis of differentially expressed genes (DEGs) after METTL13 knockdown in PC3 cells revealed significant changes in the JAK-STAT and NFκB signaling pathways, which are crucial in determining the fate of prostate cancer stem cells." (PMID 39806412, 2025).
renal cell carcinoma (1 paper, 2024). "METTL13 is lowly expressed in renal cell carcinoma, and knockdown of METTL13 promotes the PI3K/AKT/mTOR/HIF-1α pathway leading to migratory ability and invasiveness of renal cell carcinoma cells as well as elevated Vimentin and N-cadherin." (PMID 39289775, 2024).